ATF6 (activating transcription factor 6)
Diseases named in the same sentence as ATF6 in open-access papers (continued):
Sharing a sentence is not in itself a finding about the gene and the disease.
achromatopsia (continued). "In patients with achromatopsia caused by ATF6, a clinical trial (NCT04041232) has been registered to investigate whether the already approved FDA drug, glycerol phenylbutyrate (PBA), which is a fatty acid compound that facilitates protein folding, can improve retinal function." (PMID 39273686, 2024). "ROs derived from patients with achromatopsia were tested using a small-molecule ATF6 agonist (AA147)." (PMID 39422807, 2025). "Currently, six genes that cause achromatopsia have been discovered, including CNGA3, CNGB3, GNAT2, PDE6C, PDE6H and ATF6." (PMID 38298913, 2024). "Pathogenic variants in six genes (CNGA3, CNGB3, GNAT2, ATF6, PDE6C, and PDE6H) have been identified in humans with achromatopsia (OMIM 216900)." (PMID 34830323, 2021). "Interestingly, ATF6 mutations recently were implicated in the pathogenesis of the autosomal recessive cone dysfunction disorder achromatopsia (ACHM)." (PMID 29801500, 2018). "Achromatopsia, an IRD caused by ATF6 mutations, has been modeled using patient-derived ROs." (PMID 39422807, 2025). "Achromatopsia is caused by sequence variants in CNGA3, CNGB3, GNAT2, PDE6H, PDE6C, and ATF6." (PMID 39273686, 2024). "Retinal imaging of patients with ATF6 show not only foveal hypoplasia which is common in other achromatopsia mutations, but also absence of typical foveal development hallmarks." (PMID 35054919, 2022). "Future therapeutic interventions for achromatopsia, or any other AT6-associated disease conditions, must take into account that modulating ATF6 activation in cones may have catastrophic consequences for color vision." (PMID 35346303, 2022). "Interestingly, the only achromatopsia-associated gene not involved with the phototransduction cascade is the activating transcription factor 6 (ATF6), a gene important for regulating ER stress, and mutations in ATF6 have been shown to lead to ER stress." (PMID 35054919, 2022). "The similar clinical presentation between familial achromatopsia in humans and bovine recessive day-blindness led to the hypothesis that a protein-changing variant within CNGA3, CNGB3, GNAT2, ATF6, PDE6C, and PDE6H would be associated with achromatopsia of Original Braunvieh calves." (PMID 34830323, 2021). "These mice carry a premature stop codon in exon 4 and produce no ATF6 protein, similar to some ATF6 disease alleles found in patients with achromatopsia (ACHM)." (PMID 39570676, 2025). "Pathogenic variants in different genes such as CNGA3, CNGB3, GNAT2, PDE6H, ATF6 and PDE6C have been reported to be relevant to COD, cone-rod dystrophy (CORD) and achromatopsia (ACHM) diseases." (PMID 38956522, 2024). "ATF6 small molecule agonists, such as ATF6-activating (AA) compounds AA147 and AA263, and antagonists, such as Ceapin-A7, have been shown to selectively modulate the ATF6 arm of the UPR pathway, Downstream targets of ATF6 may also serve as potential targets in achromatopsia." (PMID 35346303, 2022).
steatosis (26 papers, 2012 to 2025). Increased lipid within the cytoplasm of cells. "For example, it has been shown that steatosis in zebrafish caused by acute stress is augmented by ATF6 loss, but that steatosis caused by chronic stress is reduced when ATF6 is depleted." (PMID 39056688, 2024). "A study in zebrafish showed that ATF6 deficiency prevented steatosis during chronic ER stress but exacerbated steatosis during acute ER stress." (PMID 35873545, 2022). "For example, the loss of ATF6 can prevent steatosis that is caused by chronic ER stress; however, it can enhance steatosis that is caused by acute ER stress." (PMID 34778458, 2021). "In Zebrafish, blocking ATF6 larvae prevents alcohol-induced steatosis, and ATF6 overexpression induces genes that drive lipogenesis, increases lipid production and causes steatosis." (PMID 33670323, 2021). "Using Atf6‐deficient mice, a recent study compared the contribution of ATF6 to the development of both liver and kidney steatosis." (PMID 33398919, 2021). "Our previous work using zebrafish confirmed the finding that steatosis caused by acute stress is augmented by atf6 loss, and also demonstrates that steatosis caused by chronic stress is reduced when Atf6 is depleted." (PMID 24874946, 2014). "Our recent finding that Atf6 overexpression is sufficient to cause steatosis in zebrafish definitively shows that activation of this pathway is a culprit in FLD." (PMID 24973751, 2014). "This is consistent with our finding that Atf6 overexpression causes steatosis, in part due to induction of lipid synthesis by an Srebp-independent mechanism." (PMID 24973751, 2014). "A number of studies have demonstrated that loss of one of the key UPR sensors – PERK, IRE1α or ATF6 – enhances steatosis caused by acute stress." (PMID 24874946, 2014). "Taken together, our data suggest a model by which Atf6 causes steatosis, in part, by inducing fasn and TAG synthesis by a mechanism that is independent of Srebps." (PMID 24874946, 2014). "ATF6 knockout mice fail to resolve steatosis caused by acute stress due to tunicamycin injection, suggesting that loss of ATF6 promotes fatty liver." (PMID 24874946, 2014). "This study indicates that Atf6 causes steatosis by inducing lipid synthesis; however, there are probably other aspects of the UPR that contribute to FLD." (PMID 24973751, 2014). "Here, we use genetic and genomic approaches in a well-established zebrafish model of ALD to demonstrate that blocking Atf6 prevents alcohol-induced steatosis and that overexpression of the nuclear, active form of Atf6 (nAtf6) causes steatosis." (PMID 24874946, 2014). "Blocking Atf6 in zebrafish larvae prevents alcohol-induced steatosis and Atf6 overexpression in zebrafish hepatocytes induces genes that drive lipogenesis, increases lipid production and causes steatosis." (PMID 24874946, 2014). "atf6 transcription is significantly upregulated in the liver of zebrafish with alcoholic FLD and morpholino-mediated atf6 depletion significantly reduced steatosis incidence caused by alcohol." (PMID 24874946, 2014). "It was shown that ATF6 deficiency protects against steatosis in a zebrafish model of chronic hepatic ER stress (i.e., foie gras mutant), whereas it may potentiate steatosis under acute ER stress." (PMID 37373143, 2023). "ATF6α is involved in lipid synthesis regulation, with ATF6α loss in hepatocytes limiting steatosis, but may also promote fibrogenesis in response to liver injury." (PMID 35174209, 2021). "Additionally, we previously demonstrated that Atf6 depletion suppresses steatosis caused by chronic stress." (PMID 24874946, 2014). "When only the absence of ATF6α, once challenged with tunicamycin, mice began to show signs of liver dysfunction and steatosis, showing the importance of ATF6α in lipid metabolism." (PMID 39026685, 2024).
steatosis (continued). "In this connection, we previously showed that injection of tunicamycin, which induces ER stress by inhibiting protein N-glycosylation, into ATF6α-knockout mice produced Oil Red O-staining-positive livers, resulting from steatosis and lipid droplet formation." (PMID 37380437, 2023). "Previous studies showed that ATF6 not only inhibited gluconeogenesis, but also attenuated hepatic steatosis through interacting downstream regulators." (PMID 38007457, 2023). "Other researchers observed that ATF6 plays a pathological role, ATF6 prevents alcohol-induced liver steatosis, and ATF6 overexpression induces steatosis in an SREBP-independent manner in a zebrafish alcoholic liver disease model." (PMID 34778458, 2021). "In an Atf6 knock-out mouse model where ER stress was induced with tunicamycin (1 mg/kg) for one week, an increase in steatosis and liver injury occurred." (PMID 35174209, 2021). "Although Atf6α−/− mice display no apparent developmental phenotype under normal growth conditions, Atf6α deletion severely impairs liver function and prolongs steatosis compared with wild-type mice upon ER stress." (PMID 28860159, 2017). "This is consistent with our recent finding that active Atf6 is sufficient to induce steatosis via an Srebp-independent mechanism." (PMID 24973751, 2014). "atf6 morphants had reduced steatosis incidence (p<0.05), but still displayed other gross morphological abnormalities caused by ethanol including increased liver circularity, an indication of hepatomegaly, a common feature of liver disease." (PMID 24874946, 2014). "In contrast, a more acute but stronger ER stress—perhaps most akin to the exposures used in this work—led to less efficient steatosis that was exacerbated by ATF6α knockdown." (PMID 24069029, 2013). "In support of this idea, exposure of zebrafish larvae to chronic but mild TM results in efficient induction of steatosis in the larval livers, and knockdown of ATF6α ameliorated this lipid accumulation." (PMID 24069029, 2013). "Similar to IRE1α, ATF6α also protects against ER stress-induced steatosis and lipid droplet formation in mice." (PMID 22195283, 2012). "ATF6 deficiency or overexpression of dominant‐negative ATF6 (dnATF6) in mice promoted liver steatosis in response to tunicamycin treatment or high‐fat, high‐sucrose diet, respectively." (PMID 33398919, 2021). "In addition, chronic liver ER stress was observed in the steatosis of mice strains with genetically deficient in leptin as well as genetically modified IRE1/XBP1, PERK/eIF2α and ATF6 signaling pathways." (PMID 32121602, 2020). "Together, our data demonstrate that Atf6 is necessary for alcoholic steatosis and sufficient to cause steatosis in the absence of any other stress." (PMID 24874946, 2014). "In addition, while steatosis was the most evident phenotype, upon closer examination it was discovered that after 48 hours of tunicamycin treatment, ATF6α-knockout mice became profoundly resistant to exogenous insulin." (PMID 22195283, 2012). "Another potential beneficial effect of 2′-FL that may have contributed to the observed decrease in steatosis is the counter regulation of several important factors associated with ER stress such as ATF4, ATF6, ERN1, NUPR1 indicating an overall attenuation of the ER stress response." (PMID 35782914, 2022). "All three ER stress-sensing pathways (ATF6α, PERK/eukaryotic translation initiation factor 2α (eIF2α), and IRE1α/X box binding protein 1 (XBP1)) can regulate the development of steatosis in the liver." (PMID 35873545, 2022). "Furthermore, we found that atf6 and fasn interacted epistatically to cause alcoholic steatosis by co-injecting concentrations of fasn and atf6-SPL MOs that did not have any effect on alcoholic steatosis on their own but, together, significantly reduced steatosis incidence in response to ethanol." (PMID 24874946, 2014).
steatosis (continued). "We identify activating transcription factor 6 (Atf6), one of three UPR sensors, as necessary and sufficient for steatosis and show that Atf6 activation can promote lipogenesis, providing a direct connection between the stress response and lipid metabolism." (PMID 24874946, 2014). "Here, we show that Atf6 is induced in ALD, that its activation precedes steatosis, and that knocking down Atf6 reduces alcoholic steatosis." (PMID 24874946, 2014). "Indeed, our preliminary data demonstrate that Atf6 depletion protects against steatosis caused by 0.25 μg/ml Tm (not shown), suggesting that Atf6 induction in response to Tm might function by the same mechanism." (PMID 24973751, 2014). "Thus, we illustrated that ATF6 increases SIRT1 sulfhydration by H2S production, and ameliorates steatosis and inflammation in the fatty liver." (PMID 38007457, 2023). "While Srebps are not required for the effects of Atf6 on steatosis, there does appear to be some interaction between Atf6 and Srebp2, consistent with in vitro data showing that ATF6 suppresses SREBP2." (PMID 24874946, 2014). "Moreover, steatosis can be influenced by altering the expression of key UPR mediators, including BiP, PERK, IRE1A/XBP1 and ATF6." (PMID 24973751, 2014). "Our data argues against this: (i) the full panel of Srebp targets are not induced by nAtf6 overexpression in zebrafish, (ii) Atf6 and Srebps did not epistatically interact to modify alcoholic steatosis and (iii) Srebp activation is not required for steatosis in nAtf6 TG larvae." (PMID 24874946, 2014).
Obesity (25 papers, 2014 to 2026). Accumulation of substantial excess body fat. "These molecular alterations demonstrate that vascular risk in childhood obesity begins at the transcriptomic level long before clinical symptoms emerge, highlighting the ATF6/PLAT axis as a potential biomarker for early risk assessment." (PMID 41898467, 2026). "In the context of cancer and obesity, ATF6 has been implicated in the development of obesity-related cancers." (PMID 38672148, 2024). "Obesity and type II diabetes are associated with high-fat and high-glucose concentrations, which lead to beta-cell dysfunction in the pancreas via ATF6." (PMID 34299638, 2021). "To investigate if the molecular mechanism of PH could be associated to the deleterious effects of obesity, we evaluated the gene expression of ER stress markers ATF6, Ire1α, CHOP, PERK, and eIF2α in the pulmonary artery of CTL and HFD animals fed for 4 months." (PMID 34552556, 2021). "In conclusion, the suppression of ATF6 in obesity indicates the "exhaustion" of adaptive cellular defense mechanisms, while the upregulation of PLAT points to a compensatory response to the chronic prothrombotic environment." (PMID 41898467, 2026). "The mRNA expression levels of ER stress markers (Xbp1, sXbp1, Atf4, Atf6, and Grp78) were significantly higher in the ASCs treated with hypertrophic obesity adipocyte-derived EVs than in the ASCs treated with control adipocyte-derived EVs." (PMID 36035215, 2022). "Analysis of subcutaneous adipose tissue samples revealed that the mRNA expression levels of ER stress markers (Xbp1, sXbp1, Atf6, Atf4, and Grp78) were significantly higher in the hypertrophic obesity mice than in the control mice." (PMID 36035215, 2022). "For the ATF6 pathway, we observed an opposite tendency of interaction between maternal and offspring obesity in the whole protein (p90) and after splicing (p50)." (PMID 26979740, 2016). "Collectively, our findings suggest that LBP supplementation alleviates obesity by ameliorating LD accumulation, which might be partially mediated by an ATF6/SIRT1-dependent mechanism." (PMID 38606478, 2024). "This suggests that ATF6, which plays a role in ER stress, may be involved in the development of obesity-related cancers." (PMID 38672148, 2024). "ATF6 is a novel cellular signal metabolism regulator that can modulate lipid storage and obesity." (PMID 38606478, 2024). "However, activated XBP1s and ATF6 were insufficient to increase GLP-1R’s use of Gs signaling under Tm- or obesity-induced ER stress conditions." (PMID 38376482, 2024). "Dysfunctional signaling of ATF6 may contribute to the accumulation of proteins that are misfolded and exacerbate inflammation, which is a characteristic of obesity." (PMID 38140341, 2023). "When ER stress occurs in a cell that results in sorcin (a Ca2+-binding protein that helps to maintain Ca2+ homeostasis in ER) dysfunction, it also increases the ATF6 activity, which results in the advancement of insulin dysfunction, obesity, and type II diabetes." (PMID 34299638, 2021). "ER stress markers such as GRP78-BiP, ATF6, P-IRE1α, P-PERK, and P-eIF2α were found to be elevated in several in vitro myoblast models of human obesity as well as in the SKM from both sexes of obese and diabetic rodents and obese and/or diabetic women." (PMID 39857351, 2024). "Expanding our scope beyond IRE1α, the roles of PERK and ATF6, also integral to the UPR, have garnered attention as promising targets in the battle against obesity-induced cancer." (PMID 38672148, 2024). "It is also possible that β-cells under obesity and T2D display GLP-1R’s signaling shift to Gq, due in part to insufficient XBP1s’ and ATF6′s action enhancing GLP-1R’s Gs use." (PMID 38376482, 2024). "Risk factors related to AS, such as hyperlipidemia, hypertension, and obesity, activated the ER stress-related proteins, such as IRE1, PERK, and ATF6, and aggravated the inflammatory response in macrophages." (PMID 34136067, 2021).
Obesity (continued). "Comparable trends were also observed for the ER stress markers GRP78 and ATF6, as their expression levels in the SAT were significantly elevated in obesity and decreased after physical activity (p < 0.05)." (PMID 32192153, 2020). "Our study raises the possibility that LBP exerts its effects not only by targeting SIRT1 but also by targeting ATF6, which will further ameliorate the UPR and ER stress and may represent a therapeutic strategy for obesity." (PMID 38606478, 2024). "Therefore, future studies assessing ATF6 and/or PERK pathways would be useful to gain a mechanistic understanding of UPR activation in the liver in the context of obesity and aging and in the response to dietary DHA supplementation and/or exercise." (PMID 33546405, 2021). "Obesity is often characterized by an ER stress and consequently an adaptive unfolded protein response (UPR), operated by three parallel sensors: activating transcription factor 6 (ATF6), inositol requiring enzyme 1α (IRE1α), and protein kinase R-like ER kinase (PERK)." (PMID 33210603, 2020). "Given that overexpression of ATF6 in the livers of obese animals seems advantageous in reversing the effects of CRTC2 on the gluconeogenic program, this interaction between ATF6 and CRTC2 may be a significant factor in the impairment of hepatic gluconeogenesis in obesity and type 2 diabetes." (PMID 40145401, 2025).